PODXL (podocalyxin like)
Diseases named in the same sentence as PODXL in open-access papers (continued):
Sharing a sentence is not in itself a finding about the gene and the disease.
tumor (continued). "PODXL regulates epithelial and tumor cell motility through interactions with the actin polymerization complexes, including the ERM (ezrin–radixin–moesin) family and PDZ protein Na+/H+ exchanger regulatory factors 1 and 2 (NHERF-1/2)." (PMID 38203331, 2023). "Several studies support the role of PODXL in normal and tumor cell adhesion, migration and polarity." (PMID 35711462, 2022). "These nodules then migrate and invade the adjacent stromal tissue, demonstrating the ability of PODXL to induce collective tumour budding and subsequent invasion in vivo." (PMID 34201212, 2021). "The DTHL motif of PODXL is further shown to regulate cortactin and Rac1/Cdc42 activation to enhance tumour metastasis and invadopodia formation." (PMID 34201212, 2021). "PODXL overexpression is associated with cancer hallmarks such as EMT, metastasis, invasion, survival, and resistance to drugs, all of which promote tumour aggression and poor prognosis." (PMID 34201212, 2021). "The contribution of PODXL to tumor metastasis to distal sites has been elucidated in vivo in a few studies." (PMID 32046309, 2020). "Beside TGGA datasets, Oncomine was used to further verify the differences of PODXL expression level between various tumor tissues and corresponding normal tissues." (PMID 32615943, 2020). "Then we used GEPIA and UALCAN to explore TCGA datasets, to compare the expression difference of PODXL among tumor tissues and correlated normal tissues, and the survival curves." (PMID 32615943, 2020). "A few studies have examined the involvement of PODXL in tumor cell resistance to both conventional cytotoxic agents and immunotherapy drugs." (PMID 32046309, 2020). "PODXL expression has been reported in the cytoplasm of some tumor cells, in some cases protruding toward the cell membrane, but not in the nucleus." (PMID 32615943, 2020). "All these data demonstrate the complex and crucial role of PODXL in tumor cell proliferation and tumorsphere formation in vitro as well as in primary tumor growth in vivo." (PMID 32046309, 2020). "The differences of PODXL expression level between various tumor tissues and corresponding normal tissues were obtained with GEPIA, which was a common web-based tool that can provide a quick and customizable survey of function based on TCGA and GTEx data." (PMID 32615943, 2020). "A previous study showed that PODXL-promoted tumor metastasis was mediated by activating the Ras-related C3 botulinum toxin substrate 1 (Rac1) signaling cascade or PI3K/Akt signaling." (PMID 32669966, 2020). "As PODXL is a transmembrane glycoprotein, whose high expression level and membrane expression lead to cell motility increasing, and over-activated tumor cell migration ability promotes tumor progression." (PMID 32615943, 2020). "In mice, induced overexpression of PODXL led MCF-7 cell clusters to bud off from the primary tumor and invade mouse mammary gland stroma." (PMID 31083655, 2019). "Tumor cells and immunosuppressive cells express or secrete podocalyxin-like protein 1 (PCLP1), activin-a, indoleamine-pyrrole 2,3-dioxygenase (IDO), PGE2, TGF-β, and macrophage migration inhibitory factor (MIF) in the TME to mediate NKG2D downregulation." (PMID 30813924, 2019). "We observed that the cytoplasm of tumor cells was evenly PODXL-positive staining and the tumor stroma was PODXL-negative." (PMID 29748877, 2019). "Further analysis demonstrated that PODXL expression was significantly correlated with tumor stage, indicating that PODXL was elevated in advanced tumor stage." (PMID 29748877, 2019). "Enforced expression of PODXL increased the formation and activation of invadopodia, resulting in the tumor invasion and metastasis." (PMID 29748877, 2019).
tumor (continued). "The influence of PODXL on tumor growth of OSCC was also investigated in vivo, and both the tumor volume and the tumor weight were observed to be significantly lower for HSC-2/PODXL-KO than that for HSC-2 parental cells." (PMID 30105309, 2018). "Membranous expression of podocalyxin-like protein 1 (PODXL) and low expression of the RNA-binding motif 3 (RBM3) has previously been shown to be associated with an aggressive tumour phenotype and poor prognosis in several forms of cancer, including UBC." (PMID 28293425, 2017). "PODXL is a protein that in experimental studies is associated with epithelial mesenchymal transition (EMT) and, hence, the invasion and spread of tumours." (PMID 28293425, 2017). "Dysregulation of PODXL in tumor cells was reported to increase their aggressive and metastatic capabilities, and its overexpression is associated with poor survival in breast, colon, brain, and pancreatic cancers." (PMID 28946619, 2017). "In two recent studies, knockdown of PODXL in breast cancer cell lines resulted in impaired primary tumour growth and metastasis." (PMID 27160084, 2016). "Using GSTP as a marker for neoplastic lesions and tumors areas, EZR, CLIC5 and PODXL expression was co-localized within the tumor region of serial samples of rat liver tumors after 9, 12 and 18 months of treatment." (PMID 26135398, 2015). "PODXL-expression was found to be significantly higher in PB-type as compared with I-type tumours, with the exception for ampullary PB-type tumours." (PMID 26028992, 2015). "PODXL expression by the pAb was cytoplasmic in tumor cells, but in some cases, distinct membranous expression was visible, not correlating with intensity of cytoplasmic expression." (PMID 26053486, 2015). "Membranous PODXL expression was considerably higher in PB-type as compared with I-type tumours, which is in line with the former being clinically more aggressive." (PMID 26028992, 2015). "The protein expression levels of EZR, CLIC5 and PODXL were higher in nodular and tumor areas compared to non-tumor areas or controls (p<0.05), which correlated with the qRT-PCR results." (PMID 26135398, 2015). "The results further indicate a beneficial effect of adjuvant chemotherapy on I-type tumours with membranous PODXL expression, suggesting the potential utility of PODXL as a biomarker for improved treatment stratification of these patients." (PMID 26028992, 2015). "In multivariable analysis, PODXL remained a significant prognostic factor only in I-type tumours (HR = 5.12, 95 % CI 1.43–18.31 for RFS, and HR = 7.31, 95 % CI 2.12–25.16 for OS)." (PMID 26028992, 2015). "PODXL was detected in the cytoplasm of tumor-region hepatocytes from treated rats, whereas PODXL expression was clearly nuclear in control livers." (PMID 26135398, 2015). "Membranous expression of podocalyxin-like 1(PODXL), which is a cell-adhesion glycoprotein and stem cell marker, has been found to correlate with an aggressive tumour phenotype and adverse outcome in several cancer types." (PMID 26028992, 2015). "When ampullary PB-type tumours, expressing membranous PODXL in a similar proportion to I-type tumours, were included in the analysis, the effect by adjuvant chemotherapy was even more pronounced." (PMID 26028992, 2015). "Patients with I-type tumours displaying membranous PODXL expression had a significant beneficial effect of adjuvant chemotherapy regarding 5-year OS." (PMID 26028992, 2015). "When ampullary PB-type tumours, expressing membranous PODXL in a similar proportion to I-type tumours, were included in the analysis, the beneficial value of adjuvant chemotherapy was even more pronounced." (PMID 26028992, 2015). "Membranous PODXL expression was significantly associated with a reduced RFS (HR = 2.44, 95 % CI 1.10–5.44) and OS (HR = 2.32, 95 % CI 1.05–5.12) in I-type tumours and with a reduced RFS (HR = 1.63, 95 % CI 1.07–2.49) but not OS in PB-type tumours." (PMID 26028992, 2015).
tumor (continued). "Previous studies have reported EZR or PODXL overexpression in different tumors, indicating their participation in tumor progression." (PMID 26135398, 2015). "Membranous PODXL expression was significantly higher in primary PB-type (49.5 %) as compared with I-type (17.5 %) tumours." (PMID 26028992, 2015). "In the vast majority of tumours, PODXL stained evenly throughout the cytoplasm in a granular manner, and positivity was visible in all tumour cells." (PMID 25004863, 2014). "This is unlikely due to inadequate statistical power in our study, as there were 237 cases of RHCC, suggesting a different role for PODXL in tumours of the RHC compared to the LHC." (PMID 25004863, 2014). "PODXL expression by the pAb was cytoplasmic in tumour cells, but in some cases a distinct membranous expression was seen, which did not always correlate with intensity of cytoplasmic expression." (PMID 25004935, 2014). "This is, to our knowledge, the first evidence of such difference in PODXL expression, its function possibly being dependent upon tumour location." (PMID 25004863, 2014). "The high proportion of metastasised cancers in this group supports the role of PODXL overexpression in tumour cell dissemination leading to metastases to distant organs." (PMID 25004935, 2014). "As an anti-adhesive molecule, aberrant PODXL expression has been suggested to support the disruption of cell-to-cell and cell-to-extracellular matrix adhesions, thus promoting tumour dissemination." (PMID 25004935, 2014). "In uterine endometrioid adenocarcinoma, PODXL expression is correlated with tumor grade, while its overexpression is an independent indicator of poor outcome in breast and colorectal carcinoma." (PMID 23596468, 2013). "In this study we have analyzed PODXL expression in 31 primary tumours and a total number of 140 corresponding lymph node metastases, thus providing a thorough characterization of PODXL expression in both settings." (PMID 23819542, 2013). "The clinical significance of PODXL in cancer progression has been investigated in numerous tumor types, including breast, colon and uterine carcinoma." (PMID 23596468, 2013). "In conclusion, the results from this study suggest that PODXL expression in CRC is concordant in primary tumours and corresponding lymph node metastases in individual patients, and also remains unaffected by neoadjuvant radiation therapy." (PMID 23819542, 2013). "A number of other studies have demonstrated an inverse correlation between PODXL expression and degree of tumor differentiation." (PMID 24146797, 2013). "Our results indicate that by use of full-face section analysis, a larger proportion of tumours are identified as being PODXL positive, i.e. having membranous expression, compared to TMA-based analyses (24,7% vs 8-13%)." (PMID 23819542, 2013). "A discrepancy between PODXL expression in tumours before and after radiation therapy was noted in two cases." (PMID 23819542, 2013). "Tumor specimens were obtained directly from the operating room and analyzed, using flow cytometry, for the expression of PODXL." (PMID 24146797, 2013). "Immunohistochemical PODXL expression was examined on full-face sections from all primary tumours and all 140 available lymph node metastases from 31 cases." (PMID 23819542, 2013). "The podocalyxin-like (PODXL) gene has been reported to promote the metastatic potential of tumor cells." (PMID 24179530, 2013). "Together with the anti-invasion effect mediated by the action of PODXL, miR-199a serves as a tumor-suppressor in TGCTs." (PMID 24391856, 2013). "Membranous PODXL expression was denoted in 18/73 (24,7%) primary tumours, with a high concordance between primary and metastatic lesions." (PMID 23819542, 2013). "The poor prognosis seems to be conferred by PODXL expression on the membrane of tumour cells, and predominantly at the invasive tumour front, further indicating an integral role for this protein in the progression of some tumours." (PMID 23819542, 2013).
tumor (continued). "PODXL protein expression was analyzed by immunohistochemistry in tissue microarrays with tumour samples from a consecutive, retrospective cohort of 270 CRC patients (cohort 1) and a prospective cohort of 337 CRC patients (cohort 2)." (PMID 22769594, 2012). "PODXL has also been demonstrated as being a target of tumour suppressive miRNA-199 in testicular cancer." (PMID 22769594, 2012). "PODXL mRNA levels were assessed in 62 fresh frozen tumour specimens from cohort 2, comprising 21 tumours with high protein expression and 41 tumours with low protein expression." (PMID 22769594, 2012). "A secondary aim was to examine the correlation between PODXL mRNA and protein levels and its clinical significance in a subset of the tumours." (PMID 22769594, 2012). "While PODXL is expressed in the cytoplasm in a considerable proportion of CRC tumours, it is mainly the presence of distinct membranous staining, here denoted as high expression, that seems to confer a poor prognosis." (PMID 22769594, 2012). "The aim of this study was to validate these results in two additional independent patient cohorts and to examine the correlation between PODXL mRNA and protein levels in a subset of tumours." (PMID 22769594, 2012). "In both cohorts in this study, the proportion of tumours denoted as having high PODXL expression was lower compared to our previous study, where 13.4% of the tumours displayed high PODXL expression." (PMID 22769594, 2012). "Consequently, while PODXL represents a promising target for disrupting tumor progression, careful consideration must be given to strategies that can selectively inhibit its function in tumor cells without affecting its normal physiological roles." (PMID 40508013, 2025). "Among these, PODO447 demonstrates remarkable specificity for a tumor-associated glycosylated epitope of PODXL and does not cross-react with normal adult human tissues." (PMID 40843679, 2025). "In this study, it was demonstrated that a humanized anti-PODXL CasMab, humPcMab-60, could be a promising mAb-based tool in tumor therapy." (PMID 40843679, 2025). "Our PcMabs, including PcMab-60, may contribute to the identification of quiescent PODXL-positive tumor cells and the development of therapeutic applications to target those cells." (PMID 40843679, 2025). "Furthermore, genetic silencing of PODXL or treatment with an anti-PODXL mAb markedly suppressed tumor cell clustering in vivo and effectively inhibited metastatic colonization following intravenous injection into mice." (PMID 40843679, 2025). "Acts as a tumor suppressor; suppresses tumorigenicity via specific editing in PODXL gene." (PMID 40852728, 2025). "Furthermore, humPcMab-60 exerted antibody-dependent cellular cytotoxicity and complement-dependent cytotoxicity against PODXL-expressing cell lines and showed antitumor effects against the tumor xenografts." (PMID 40843679, 2025). "Moreover, tumor-restricted glycosylation patterns have allowed the development of tumor cell–selective therapeutic anti-PODXL antibodies." (PMID 36735782, 2023). "There were differences in tumor morphology between high– and low–surface PODXL conditions." (PMID 36735782, 2023). "Moreover, in GC, the ADAR2 activity on the PODXL (podocalyxin-like) gene at codon 241, causing His-to-Arg substitution, indicated that PODXL is one of the ADAR2-editing targets responsible for its tumor-suppressive function." (PMID 37958449, 2023). "In contrast, tumor weight was significantly decreased after inducing PODXL knockout in hEPSCs." (PMID 36373710, 2022).
tumor (continued). "High PODXL has also been associated with poor tumour differentiation and estrogen- and progesterone-receptor-negative tumours." (PMID 34201212, 2021). "Therefore, to validate the effect of PODXL expression on CRC metastasis, PODXL protein levels were evaluated using IHC in 44 CRC tumor-tissue samples and in 20 normal-tissue samples." (PMID 34440856, 2021). "Moreover, PODXL knockdown significantly impedes tumour dissemination and suppresses tumour colonisation." (PMID 34201212, 2021). "Even though a correlation between PODXL expression and tumor prognostic value has been reported, details of an underlying mechanism remain unclear." (PMID 34440856, 2021). "Additionally, PODXL overexpression promotes tumour spheroid formation in three-dimensional assays, consistent with the notion that PODXL promotes free-floating tumour clusters." (PMID 34201212, 2021). "While the exact mechanisms of PODXL in tumourigenesis are not completely understood, studies in human cancer cell lines suggest that PODXL may directly contribute to tumour aggression by facilitating tumour migration, invasion, metastases, and chemoresistance." (PMID 34201212, 2021). "According to these reports, it could be deduced that high expressed PODXL promoted tumor progression by enhancing a series of cell changes such as EMT, cell migration and invasion." (PMID 32615943, 2020). "Because PODXL has been suggested to promote tumor growth, invasion, and metastasis, high PODXL expression could have adverse effects on overall survival (OS), disease-specific survival (DSS), and disease-free survival (DFS) in several cancers." (PMID 33088928, 2020). "Additionally, PODXL has been shown to induce collective tumor migration and invasion, as well as tumor budding of MCF-7 cells both in vitro and in vivo." (PMID 32046309, 2020). "PODXL downregulation could inhibit tumor development, as shown by the inhibition of epithelial mesenchymal transformation, invasion, and metastasis in vitro and reduction of tumorigenesis in vivo." (PMID 32206039, 2020). "Furthermore, we proved that silencing PODXL in GC cell lines led to the inhibition of tumor growth and metastasis in nude mice, consistent with above study." (PMID 29748877, 2019). "Additionally, mounting evidence illustrated that PODXL level was significantly correlated with clinical features, such as advanced tumor stage, high-grade stage and so forth." (PMID 29748877, 2019). "•PODXL has an important role in tumor growth in vitro and in vivo." (PMID 30105309, 2018). "We further investigated whether PODXL affects OSCC tumor growth in vivo by comparing the growth of SAS and three SAS/hPODXL-KO cell lines that were transplanted subcutaneously into nude mice." (PMID 29854293, 2018). "Our findings provided that miR-509-3-5P, one of the tumor suppressor, could prevent tumor invasion and lymph node metastasis via targeting PODXL in GC, and act as a novel prognostic indicator for GC." (PMID 28432273, 2017). "After antibody staining and optimization, PODXL expression could be evaluated in 262/264 (99.2%) tumours." (PMID 28293425, 2017). "Moreover, some studies verified that overexpression of PODXL was correlated strongly with advanced clinicopathological features (poor differentiation, advanced tumor stage etc.)and poor prognosis." (PMID 28432273, 2017). "Taken together, PODXL, as a tumor promoter, was involved in the invasion and metastasis of GC." (PMID 28432273, 2017). "With respect to tumor type, evident correlation between the PODXL expression and OS was observed." (PMID 28881743, 2017). "After adding tumour type as a factor into the multivariable Cox regression analysis of the entire cohort, together with both PODXL and RBM3, RBM3 expression remained significant (HR 1.84, 95% CI 1.09–3.10, p = 0.022), but not PODXL expression (HR 1.43, 95% CI 0.77–2.67, p = 0.257)." (PMID 28293425, 2017).